MUC2 (mucin 2, oligomeric mucus/gel-forming)
Diseases named in the same sentence as MUC2 in open-access papers (continued):
Sharing a sentence is not in itself a finding about the gene and the disease.
cancer (continued). "Comparison between patients categorized according to biomarker expression, using formula A, i.e. [KLK6/CEACAM5 + SLC35D3/CEACAM5 + POSTN/18S rRNA -MUC2/CEACAM5], with regard to risk for recurrence of disease and cancer death and observed recurrence 3 and 5 years after curative surgery." (PMID 32049988, 2020). "Thus, our bioinformatic analyses using the Oncomine and PrognoScan databases indicate that MUC2 and IL-6 expression are involved in cancer progression." (PMID 28725043, 2017). "Successful suppression of MUC2 proteins in CT26 cancer cells was demonstrated by western blotting." (PMID 28725043, 2017). "While the role of MUC2 protein in these tumors remains unclear, the mucinous phenotype is thought to provide a protective environment for cancer cells to thrive." (PMID 29290997, 2017). "MUC2 and IL-6 were localized in the cytoplasm of the cancer cells." (PMID 28725043, 2017). "MUC2 over-expression is an adverse prognostic factor in cancers." (PMID 27835575, 2016). "Considering that the upregulation of COX-2 expression in the TAMs and MUC2+ cancer cells was largely concomitant and consistent, we speculated that the regulation of COX-2 expression in these two cell types could be inherently linked." (PMID 24324582, 2013). "We found a significant correlation between the MUC2 expression level and the cancer histotype." (PMID 24324582, 2013). "All these findings revealed that MUC2 can concurrently exert M2-polarizing and COX-2-inducing effects on TAMs, by which it causes an imbalanced TAM M1-/M2-polarization pattern and induces local PGE2 synthesis (in both TAMs and cancer cells)." (PMID 24324582, 2013). "The inhibitors of histone deacetylation and DNA methylation could have a different synergistic effect of MUC2 mRNA on cancer cells." (PMID 23347460, 2013). "Interestingly, in our study, TAMs with high COX-2 expression were predominantly M2 polarized, and vice versa; the majority of M2 TAMs in the MUC2++/+++ cancer tissues were COX-2+." (PMID 24324582, 2013). "We found that, regardless of the overall MUC2 expression level, the density of CD68+COX-2+ TAMs was significantly higher in the cancer islets, in which MUC2 molecules were vigorously secreted, than in the stromal regions, in which MUC2 molecules were scarcely secreted (p<0.001, ANOVA)." (PMID 24324582, 2013). "Because MUC2 molecules are frequently expressed in mucinous cancers, we hypothesized that the secreted MUC2 molecules allow cancer cells (with the elevated level of PGE2) to more easily survive chemotherapy." (PMID 24324582, 2013). "The increased MUC2 expression in intestinal metaplasia in the neighborhood of the carcinomas may play an important role in gastric carcinomas or IPMN." (PMID 23347460, 2013). "Alteration of MUC2 expression may contribute to change in growth regulation, immune recognition, cellular adhesion, carcinoma-host and other cellular interactions, which may influence the invasive and metastatic capabilities of the cancer." (PMID 23347460, 2013). "Unlike the less consistent expression patterns of MUC1, MUC6 and MUC5AC in normal and cancer tissues, MUC2 levels were always measured low in normal endometrial and cervical tissue, and elevated MUC2 expressions were specifically found in various neoplastic lesions." (PMID 22417007, 2012). "MUC1 was expressed in 51 (81.0%), and MUC2 was expressed in 18 (28.6%) carcinomas." (PMID 23101681, 2012). "However, MUC5AC often showed co-expression of MUC2, indicating that the cancer still has goblet cell lineage, and its gastric differentiation may simply be superficial." (PMID 29786668, 2018). "Therefore, MUC2 may play an important role in colon carcinoma metastasis and predict cancer recurrence." (PMID 28725043, 2017). "Thus, it is intriguing that MUC2 may induce a systemic antitumor immune response and may have therapeutic value in the treatment of IL-6-secreting cancers." (PMID 25322805, 2014).
cancer (continued). "Interestingly, known sequence variations in other species have elicited functional differences in cancer incidence, induction of virulence from pathogens, bacterial mucolysis, amongst others, suggesting that the heterogeneity of MUC2 plays an important role in many different biological processes." (PMID 23349743, 2013). "Their findings indicated that MUC2 may be used as an immune suppressor by cancer cells." (PMID 24324582, 2013). "It was previously reported that cancer-derived MUC2 could initiate intracellular signaling by binding to the macrophage scavenger receptor (MSR1) on the surface of infiltrating monocytes/macrophages, promoting the upregulation of intracellular COX-2 gene expression in these cells." (PMID 24324582, 2013). "However, the results regarding correlations of MUC2 expression in cancer are contradictory." (PMID 23347460, 2013). "Since we observed that the MUC2 expression level affected the M1/M2 ratio of the TAMs in the evaluated cancer tissues, we further explored whether this local immunological change could exert a substantial impact on the 5-year survival of the enrolled cancer patients." (PMID 24324582, 2013). "MUC1, MUC2, MUC5AC, and MUC6 were the most commonly analyzed mucins across cancer types according to this literature review." (PMID 39886661, 2024). "AoV cancer typically exhibits a desmoplastic stroma and commonly expresses MUC1, MUC5AC, MUC6, and MUC2." (PMID 38893239, 2024). "For example, C0 FXYD5+ TCs are abundantly present in cancerous tissues, whereas C2 MUC2+ TCs and C4 OTOP2+ TCs are predominantly present in normal and para-cancer tissues." (PMID 39717768, 2024). "Next, we analyzed the correlation between the expression levels of MUC2, MUC5AC, and MUC6 and various clinicopathological factors in the 68 patients with AoV cancer." (PMID 38893239, 2024). "Epigenetic regulation of mucin expression, such as MUC1, MUC2, MUC4, MUC5AC and MUC17, has been reported to be controlled by DNA methylation in a variety of cancer cells." (PMID 36778111, 2023). "MUC1, MUC2, MUC5AC and MUC6 were the most commonly analysed mucins across all three cancer types according to this literature review." (PMID 37958425, 2023). "Among the seven subclusters of cancer cells, cancer cell subcluster 1 specifically expressed high levels of REG4, FCGBP and MUC2, which are considered markers of goblet cells." (PMID 36690709, 2023). "Few cancer cells expressed marker genes of differentiated cell types such as CA2 (enterocyte marker) and MUC2 (goblet marker)." (PMID 35974387, 2022). "However, similarly to previous studies, analysis of the effect of MUC2 levels on DFS shows that high MUC2 levels are protective while patients with low levels of MUC2, which may reflect a more dedifferentiated state of cancer cells, have a lower DFS (HR = 2.54, p=0.023)." (PMID 35131032, 2022). "The intersection of these lists revealed that three genes (MUC2, CRACR2A, SEC16A) were significantly up-regulated in carcinomas-muc of all tested cancer types compared to controls." (PMID 33947930, 2021). "Except that, the probability of some differential expression genes, such as MUC2, CLCA1, REG4, and FGF3 can be used as prognostic biomarkers in NSCLC is worth exploring because they have been reported as a biomarkers in other cancers as well." (PMID 33927719, 2021). "Immunohistochemically, the cancer cells exhibited strong expression of “intestinal” differentiation markers, including CDX2, MUC2, and MUC5AC." (PMID 34487254, 2021). "In this study, we have demonstrated that the up-regulation of MUC2, SEC16A and CRACR2A is the common denominator of all carcinomas with mucinous differentiation studied here." (PMID 33947930, 2021).
cancer (continued). "Chemoresistance of MCC has been attributed to the abundant extracellular MUC2 protein that may act as a barrier against drug delivery or immune infiltration, and forms an immunosuppressive/hypoxic microenvironment that impairs treatment efficacy and allows cancer cells to thrive." (PMID 32811515, 2020). "Both, poorly cohesive and non-poorly cohesive cancers with ≥ 10% SRCs, were more frequently MUC2, MUC5AC, or ABPAS positive compared to cancers with < 10% SRCs." (PMID 32488651, 2020). "Many other cancer-related genes showed up differentially expressed in PDAC, including MUC2, MUC5B, MUC13, ALDH3A1, CDCA7, and CCL2." (PMID 31379917, 2019). "Other research, comparing different subtypes of CCs, confirmed that the most abundantly represented mucins in these cancers were MUC1 (~66%) and MUC5AC (~61%), followed by MUC2 (~24%) and MUC6 (~14%)." (PMID 30875782, 2019). "Conversely, decreased MUC2 expression contributes to CRC by promoting interleukin-6-induced epithelial to mesenchymal transition (EMT), thereby influencing the invasiveness of cancer cells." (PMID 29967641, 2018). "MUC2 protein expression was significantly higher in LS174T cells than in HT-29 cells and all other cancer cell lines tested." (PMID 28725043, 2017). "MUC2 participates in STAT3-induced cell migration and E-cadherin downregulation in HT-29 cancer cells." (PMID 28725043, 2017). "Strong MUC2 expression and low IL-6 and CD68 expression were detected in the same specimen from a patient with stage IIA cancer (upper left and upper right)." (PMID 28725043, 2017). "Successful suppression of the MUC2 protein in HT-29 and LS174T cancer cells was demonstrated by western blotting." (PMID 28725043, 2017). "It has been shown previously that expression of mucin genes (including MUC1, MUC2, MUC3, MUC4 and MUC5AC) is regulated by DNA methylation at promoter regions in cancer cell lines." (PMID 27283771, 2016). "MGL is able to interact with various types of cancer-related-mucins from which two are extensively studied, namely mucin 1 (MUC1) and mucin 2 (MUC2)." (PMID 27153100, 2016). "We have also found that the methylation status, mRNA expression, and mucin core protein expression were well correlated with each other for MUC1, MUC2, and MUC4 in cancer cell lines." (PMID 24714692, 2014). "The expression profiles of MUC2 and MUC3 were also considered, since these mucins had decreased expression in cancer lesions." (PMID 24722639, 2014). "We also showed that three mucin genes (MUC1, MUC2 and MUC4) expression in cancer cell line was regulated by DNA methylation." (PMID 24714692, 2014). "The expression rates in cancer lesions (more than 5% of carcinoma cells stained) were MUC1, 51.7% (31/60); MUC2, 26.7% (16/60); MUC3, 55% (33/60); MUC4, 51.7% (31/60); MUC5AC, 33.3% (20/60); MUC6, 10% (6/60) and MUC16, 8.3% (5/60)." (PMID 24722639, 2014). "A number of CD68-COX-2+ cancer cells were observed surrounding the CD68-COX-2+ TAMs, particularly in the specimens from the high MUC2 expression group." (PMID 24324582, 2013). "We found that most of the TAMs, which were closely surrounded by MUC2+ cancer cells, exhibited upregulated COX-2 expression (i.e., an increased ratio of CD68+COX-2+ cells/total CD68+ cells in the cancer islets)." (PMID 24324582, 2013). "Upon examining the cancer tissue sections, we observed that the intra-islet density of M1-polarized TAMs (CD68+ HLA-DR+ or CD68+ iNOS+) was significantly lower in the high MUC2 expression group than in the low MUC2 expression group (p<0.01, Student’s t test)." (PMID 24324582, 2013). "Immunoreactivities to Ki-67, EMMPRIN, and VEGF were weaker in the intestinal-type carcinomas than in the intestinal component of the MT (p < 0.05), while it was the opposite for CD44, MUC-2, and MUC-6 (p < 0.05)." (PMID 18266006, 2008).
cancer (continued). "Immunoreactivities to Ki-67, EMMPRIN, and VEGF were weaker in IT carcinoma than in the MT intestinal portion (p < 0.05), while the opposite was true for CD44, MUC-2, and MUC-6 (p < 0.05)." (PMID 18266006, 2008). "Investigation of the degree of differentiation of the two cancer cell lines into the colonic mucosal epithelium revealed higher gene expression of alkaline phosphatase (ALP) and mucin 2 (MUC2), which are colonic mucosal epithelial markers, in CT26 cells compared with HT29 cells." (PMID 39859378, 2025). "However, dysregulation in mucin expressions, such as MUC1, MUC2, MUC4, MUC5AC, and MUC16, have been observed in many cancer cells." (PMID 40699805, 2025). "A study by Santini reported the lack of a prognostic role for MUC2 expression in AoV cancer, albeit with a small sample size." (PMID 38893239, 2024). "Therefore, we investigated the clinical significance of MUC1, MUC2, MUC5AC, and MUC6 expression in AoV cancer." (PMID 38893239, 2024). "MUC1, MUC2, MUC4, MUC5AC, and MUC6 are currently the most widely covered in the literature regarding their role in the progression from normal colonic tissue to cancer." (PMID 36900282, 2023). "In fact, our results indicate that MUC2 expression may play a role in differentiating CMS3 and CMS4 cancers." (PMID 34475526, 2022). "Furthermore, the cancer cells exhibited strong expression of “intestinal” differentiation markers, including CDX2, MUC2, and MUC5AC." (PMID 34487254, 2021). "We show that, independent of cancer type, carcinomas with mucinous differentiation not only display elevated expression of MUC2 but also complementary genes involved in MUC2 packing, folding and transport." (PMID 33947930, 2021). "MUC2 silencing may promote CRC metastasis by interleukin-6-induced EMT, which contributes to the invasiveness of cancer cells." (PMID 29967641, 2018). "We also found that six genes (TBP, EP400, DSPP, MUC21, MLLT3, and MUC2) were under negative selection in more than five cancer types." (PMID 28938601, 2017). "In this study, we investigated the relationships between mucin expression and clinicopathologic factors in 60 SBC cases, in which expression profiles of MUC1, MUC2, MUC3, MUC4, MUC5AC, MUC6 and MUC16 in cancer and normal tissues were examined by immunohistochemistry." (PMID 24722639, 2014). "In the 108 cases, the positive expression rates (more than 5% of carcinoma cells stained) of each mucin antigen were MUC1, 47.2% (51/108); MUC2, 71.3% (77/108); MUC3, 18.5% (20/108); MUC4, 93.5% (101/108); MUC5AC, 50.0% (54/108); MUC6, 4.6% (5/108) MUC16, 16.7% (18/108) and MUC17, 86.1% (93/108)." (PMID 25551773, 2014). "MUC2 expression was significantly lower in adenomatous polyps compared to normal, but not carcinoma." (PMID 25423035, 2014). "Among mucins with decreased expression in SBC, MUC2 showed supranuclear expression in normal epithelium, but not in carcinoma cells; and MUC3 showed apical expression in normal epithelium, but not in carcinoma cells." (PMID 24722639, 2014). "In this context, it was important to examine the possibility that γ-secretase inhibition could differentially affect MUC2 and MUC5AC expression by cancer cells." (PMID 23409082, 2013). "As a result, we found that the MUC2 overexpression (immunostaining ++/+++) was significantly correlated with a reduced ratio of M1/M2 TAMs (p<0.001), an increased density of COX-2+ TAMs (p<0.001) and an increased density of COX-2+ cancer cells (p=0.017)." (PMID 24324582, 2013). "Moreover, either in the cancer islets or in the stromal regions, the density of CD68+COX-2+ TAMs was significantly higher in the high MUC2 expression group than in the low MUC2 expression group (p<0.001, ANOVA)." (PMID 24324582, 2013).
cancer (continued). "The detrimental role of MUC2 may be mediated by the imbalanced M1 and M2 polarization of TAMs and could be facilitated by the vigorous PGE2 synthesis raised in COX-2+ TAMs and cancer cells." (PMID 24324582, 2013). "Other antibodies directed against the mucins MUC1, MUC2 and MUC4 should also be evaluated, since these proteins are heavily glycosylated, and altered glycosylation in cancer may influence the reactivity to such antibodies." (PMID 19236510, 2009). "GFP measurement could not demonstrate an increase in cancer cell killing by the removal of MUC2 protein in either of the cell lines, using any of the E/A PBMC numbers, in either a 2D or 3D setting." (PMID 39926604, 2024). "The IHC profile of different histological types of carcinomas allows them to be distinguished; for example, the pancreaticobiliary type expresses CK7 and mucin 5a (MUC5a), and the intestinal type expresses CK20, caudal-type homeobox 2 (CDX2) and mucin 2 (MUC2)." (PMID 36008616, 2022). "Because MUC2 was strongly correlated with the intestinal histological type in our study (P = 0.004), it seems that the correlation between MUC2 and HER2 expression may reflect a linkage between the intestinal differentiation of cancer cells and HER2 expression." (PMID 26060493, 2015). "Additionally, in the whole section (cancer islet+stromal region), the mean ratio of CD68+COX-2+ TAMs/total CD68+ TAMs was significantly higher in the high MUC2 expression group than in the low MUC2 expression group (p<0.001, Student’s t test)." (PMID 24324582, 2013). "Notably, the most distal carcinoma was located in the duodenal bulb and appeared to arise from mucosa containing gastric fundic glands, gastric foveolar epithelium, CD10-positive cells, MUC2-positive cells, and Brunner's glands, suggesting origin from ectopic gastric mucosa in the duodenum." (PMID 41591723, 2026). "Here, we show that MUC2, an intestinal marker not expressed in the esophagus or stomach, is strongly expressed in both BE and GIM, and its expression decreases during cancer development." (PMID 36994101, 2023). "In Case 2, the neoplastic and carcinoma cells were strongly positive for MUC5AC and MUC6 but only focally positive or negative for MUC1, MUC2, CDX2, CK7, and CK20, suggesting that this immunophenotype was compatible with the gastric type." (PMID 27656307, 2016). "In Case 1, the dysplastic and carcinoma cells were strongly positive for CK7, MUC1, and MUC6 but negative or only focally positive for CK20, MUC2, CDX2, and MUC5AC." (PMID 27656307, 2016). "It shows a strong interaction of the PBMCs and a strong expansion of E/A PBMCs when co-cultured with cancer cells, yet no drastic visual differences between CTRL and MUC2 K.O. could be observed at this point." (PMID 39926604, 2024). "Therefore, suppression of MUC2 did not affect cell growth in the HT-29 and LS174T human cancer cell lines." (PMID 28725043, 2017).